ROCK2 (Rho associated coiled-coil containing protein kinase 2)
Diseases named in the same sentence as ROCK2 in open-access papers (continued):
Sharing a sentence is not in itself a finding about the gene and the disease.
tumor (continued). "Other recent studies have also revealed functional differences between ROCK1 and ROCK2 in regulating the actin cytoskeleton and other cellular functions in non-tumor cells." (PMID 26725045, 2016). "Cross-breeding the conditional mice to other mice that were genetically engineered to develop lung cancer showed that the presence of either ROCK1 or ROCK2 alone was sufficient to allow tumour cells to divide." (PMID 26950944, 2016). "After thorough in vitro characterization of cells lacking ROCK1 and ROCK2, we investigated the roles of ROCK1 and ROCK2 in tumorigenesis in vivo using genetically engineered mouse tumor models." (PMID 26765561, 2016). "Our in vivo tumor growth study strongly suggests that inhibitors targeting ROCK2 have great potential to serve as a chemo-sensitizing therapy in HCC." (PMID 27213590, 2016). "While the expression levels of Rho A, ROCK2 and moesin were positively correlated with Tumor differentiation, and TNM stage." (PMID 26846339, 2016). "Evidently, downregulation of ROCK1 or ROCK2 constitutes a critical step in the tumor suppressor activity of miR-144." (PMID 25912304, 2015). "Animal models have revealed that ectopic ROCK2 activation in established tumors is sufficient to drive metastasis of tumor cells into the surrounding stroma." (PMID 24405853, 2014). "In the present study, we investigate the unique cellular roles of ROCK1 & 2 proteins in endothelial cells and angiosarcoma tumor progression using stably expressed short hairpin RNA (shRNA) plasmids specific for ROCK1 or ROCK2." (PMID 22934846, 2013). "Furthermore, we examined the expression of ROCK2 and Drp1 in 68 tumour-adjacent and 282 CCA tissues, including 58 iCCAs, 123 pCCAs, and 101 dCCAs, using IHC analysis." (PMID 40615369, 2025). "Immunohistochemical (IHC) analysis results indicated that, compared to that in the adjacent non-tumour tissues, the frequency of ROCK2-positive cells was higher and the staining intensity was stronger in CCA tissues from patients who showed a poor response to Pemigatinib." (PMID 40615369, 2025). "Recent studies have established a connection among ROCK2, tumour development, and drug resistance." (PMID 40615369, 2025). "The ROCK2/STAT3 pathway has become a major research direction in tumor immunity." (PMID 36982538, 2023). "Furthermore, due to the high proportion of hexokinase 2 (HK2)-positive PCs in tumors, reducing HK2/ROCK2 through shRNA or inhibitors can reduce the contractility of tumor PCs to rebuild the vascular system and thus improve drug delivery." (PMID 37666813, 2023). "Tumor suppressor miR-101 plays a crucial role in cisplatin resistance and EMT of NSCLC by targeting Rho-associated coiled-coil-containing protein kinase 2 (ROCK2)." (PMID 36778005, 2023). "Furthermore, in vivo assays showed that T4O had the potential to inhibit PC cell proliferation and decrease EMT biomarkers, KI67, PCNA and ROCK2 in tumor tissues." (PMID 35322742, 2022). "However, knockdown of SNORA71A has an opposite effect on the tumor size and the expression of ROCK2 and EMT markers." (PMID 35100495, 2022). "Notably, the mRNA levels of ROCK2 were significantly increased in the tumor tissues of mice injected with SNORA71A‐overexpressing MDA‐MB‐231 cells compared to those in the control mice." (PMID 35100495, 2022). "Therefore, the contribution of ZFAS1/miR-3924 in tumor metastasis via the RHOA/ROCK2 pathway was reported, confirming its potential regulatory effect on RHO GTPase members." (PMID 34771549, 2021). "Moreover, ROCK2 overexpression induces resistance to apoptosis and chemotherapy, thereby conferring tumor recurrence." (PMID 33692332, 2021). "Doppler ultrasound analysis of microbubble perfusion revealed that depletion of HK2 in TPC enhanced A549 tumor blood flow and perfusion in mice as compared with scramble control group, while overexpression of ROCK2 in HK2-depleted TPC reduced the enhanced tumor blood flow and perfusion observed." (PMID 34650057, 2021).
tumor (continued). "circCUL2 may function as a tumor suppressor and regulator of cisplatin sensitivity through miR-142-3p/ROCK2-mediated autophagy activation, which could be a key mechanism and therapeutic target for GC." (PMID 33153478, 2020). "Finally, we further determined that Lin28A promoted tumor growth and metastasis through the interaction with ROCK2 in vivo experiments." (PMID 30266988, 2019). "In this study, we expanded these observations and showed that when ROCK2 expression was stably downregulated in OS cells, tumor growth was significantly inhibited in NSG mice and, notably, tumors completely lost the capability to disseminate and to form spontaneous metastases in the lungs." (PMID 31878963, 2019). "There are several reports on the role of ROCK2 in tumor progression and in normal differentiation." (PMID 31488179, 2019). "We have shown that the inhibition of RhoC and ROCK2 sensitizes tumor cells to irradiation." (PMID 31488179, 2019). "In addition, in tumor cells, Rho/ROCK2 signaling pathway activation leads to increase cytoskeleton dynamics and cell invasion." (PMID 30266988, 2019). "Our results are in line with these findings and suggest that targeting YAP could be a rational strategy to inhibit multiple effects of the ROCK2/YAP axis that affect the invasive phenotype of tumor cells." (PMID 31878963, 2019). "Similarly, these results indicated that ROCK2 knockdown decreased not only the tumor growth but also the metastasis and invasion of OC cells in vivo." (PMID 30266988, 2019). "Similarly, overexpression of ROCK2, protected tumor cells against radiation while its inhibition increased radiosensitivity in vitro." (PMID 31488179, 2019). "However, since there is still some debate surrounding a possible pathogenetic role of onconeural antibodies, it is worthwhile to consider ROCK2’s function in both tumor and brain." (PMID 28554330, 2017). "We suspect the observed reduction in tumor growth in the ROCK2 knockdown tumors is due, in part, to paralog-specific regulation of cell cycle, survival, and checkpoint modulators that contribute to central processes previously shown to be regulated extensively by the ROCK proteins." (PMID 28709411, 2017). "In particular, the dramatic effect of combined Y27632 and cisplatin in inhibiting tumor growth over that of cisplatin alone in nude mice model indicates that the activation of ROCK2 may be crucial for maintaining the chemoresistance of HCC cells." (PMID 27213590, 2016). "The functional differences for ROCK1 and ROCK2 in tumor and non-tumor cells could be explained by their variations in expression levels, subcellular locations, and interaction partners in individual cell types." (PMID 26725045, 2016). "ROCK1 and ROCK2, both containing a miR-144-binding site in the 3′-UTRs, were selected for further experimental validation, in view of their critical roles in tumor cell proliferation and invasion." (PMID 25912304, 2015). "Similarly, enrichment of ROCK1 and ROCK2 proteins were detected chiefly in tumor tissues, relative to normal bone tissues." (PMID 25912304, 2015). "Many human cancers demonstrate increased ROCK2 activity, which can augment tumor invasiveness." (PMID 24405853, 2014). "A recent study has shown that while the loss of either ROCK1 or ROCK2 had no negative impact on tumorigenesis in mouse models of non-small cell lung cancer and melanoma, the loss of both isoforms blocked tumor formation owing to inhibiting cell cycle progression and tumorigenesis." (PMID 35043239, 2022). "Furthermore, the tumour microenvironment can regulate ROCK2-Myosin II to support tumour growth." (PMID 33082334, 2020). "Inhibition of ROCK2 therefore could be useful in sensitization of tumor cells to irradiation." (PMID 32443784, 2020). "In addition, ROCK2 was also present in tumor cells at resection margins (Fig EV1B)." (PMID 28031255, 2017).
tumor (continued). "We subcutaneously implanted CCA cells, in which either ROCK2 alone was knocked down or ROCK2 and UBA52 were knocked down, into nude mice to monitor tumour growth." (PMID 40615369, 2025). "The posttranslational regulation of ROCK2 mediated by GASC1/FBXO42 axis provides a delicate control of ROCK2 protein stability during HCC initiation and tumor growth." (PMID 33692332, 2021). "Subsequently, we investigated a potential link between GASC1 and ROCK2 protein levels in tumor specimens from HCC patients and identified a positive correlation between GASC1 and ROCK2 protein expression." (PMID 33692332, 2021). "Specifically, we observed that the heterogeneity of GASC1 expression determined the tumor-initiating capacity of individual cells and a functional link between GASC1 and the antiapoptotic ROCK2 pathway, as well as the effect of GASC1 on ROCK2 levels." (PMID 33692332, 2021). "Knockout studies of ROCK1 and ROCK2 have shown that ROCKs are essential for cell cycle progression and tumorigenesis, but in order to achieve efficient tumor growth inhibition, it is preferable to target both ROCK1 and ROCK2 to avoid redundancy." (PMID 31888022, 2019). "The effect of the expression and activity of ROCK2 and YAP on tumor progression was analyzed in 175 OS primary tumors." (PMID 31878963, 2019). "In tumor cells, ROCK1 and ROCK2 have recently been reported to have functional differences in regulating adhesion, migration, proliferation, and gene expression, but the underlying mechanisms are not fully understood." (PMID 26725045, 2016). "There are several reports to illustrate the decrease in tumor suppressive microRNAs which directly regulate expression of ROCK1 and ROCK2 in other type of cancers." (PMID 27203208, 2016). "Overall, it appears that within the systems studied ROCK1 and ROCK2 perform the same roles, and that ROCK proteins are indispensable for cell proliferation and hence tumor development." (PMID 26765561, 2016). "ROCK2 is an important metastatic gene found to be up-regulated in HCC samples, therefore miR-139 can exert its tumor suppressive function through inhibiting of ROCK2." (PMID 24690114, 2014). "Tumor weight was significantly reduced in ROCK1 & 2 knockdown tumors compared to control tumors, with ROCK2 shRNA tumors displaying smaller tumors than those formed by ROCK1 knockdown cells." (PMID 22934846, 2013). "High ROCK2 levels are linked to male gender, alcohol consumption, advanced stage, and high CAF density in the stroma, but not to smoking, tumor site, treatment, histological grade, margin status, or recurrence." (PMID 39928309, 2025). "miR-185-5p targets ROCK2, ELK1, ELK3, IGF2, RAGE, BCL2, BCL2L1, and many other genes to suppress tumor cell migration and invasion." (PMID 35223832, 2022). "In this experiment, the tumor environment only caused increases in RhoA, ROCK1 and ROCK2, and other components of this signaling pathway were not elevated." (PMID 35811723, 2022). "Both RT-PCR and western blot analysis indicated that the conditioned medium of 3-BP or/and DOX pre-treated tumor cells could still up-regulate HK2 and ROCK2 expression in NSCLC/HCC-derived NPC as compared to untreated NPC group." (PMID 34650057, 2021). "We further observed an overall negative association between NME4 and tumor invasion markers like genes encoding matrix-degrading proteases (MMP7, ADAM17) and actin cytoskeleton remodelers (ROCK1, ROCK2, LIMK2, CFL2, MYO5A)." (PMID 34674701, 2021).
tumor (continued). "The scrambled control and ROCK1 shRNA xenograft tumor-bearing mice were largely ulcerated and openly hemorrhaging on the primary lesion, however ROCK2 shRNA xenograft tumors exhibited no significant dermatological ulcerations." (PMID 28709411, 2017). "The presence of either ROCK1 or ROCK2 was sufficient to support tumour growth, but tumours did not form if both were missing." (PMID 26950944, 2016). "These putative tumor suppressor functions of Rock1 and Rock2 do not appear to be a consequence of differential expression as the absolute concentration of the two isoforms was found to be similar by SRM." (PMID 26765561, 2016). "Furthermore, miR-144 appears to function as a tumor suppressor in the development and progression of OS via downregulation of ROCK1 and ROCK2." (PMID 25912304, 2015). "In contrast, differentially expressed genes between CECs isolated using the cmHsp70.1 mAb- versus EpCAM mAb-based approach, such as ROCK2, STAT3 and CD82, are related to EMT, stemness and endometrial cell proliferation, which are regulated via up-regulated CD44/STAT3 signaling in tumor cells." (PMID 39519195, 2024). "Tumour cells from mice injected with siHNRNPC‐silenced PanC‐1/NF co‐cultures had significantly decreased HNRNPC, RhoA, ROCK2 and YAP expression, suggesting that radiation resistance is mediated via HNRNPC and the downstream RhoA/ROCK2/YAP signalling pathway in PC." (PMID 35277915, 2022). "Importantly, depletion of HK2/ROCK2 restored the blood vessel supporting function of TPC, while treatment of HK2 inhibitor induces MLC2-driven tumor vasculature remodeling to enhance chemotherapy delivery and efficacy against tumor growth." (PMID 34650057, 2021). "To determine whether 3-BP or/and doxorubicin could affect tumor cells mediated pericyte’s glycolytic change, we examined the effect of conditioned medium harvested from cancer cells pre-treated with 3-BP or/and doxorubicin on pericyte-HK2 and ROCK2 expression." (PMID 34650057, 2021). "Survival was also found to be decreased in BrafV600E:Rock2f/fmice as well as in combination with Ptenf/f, suggesting that unlike in the NSCLC model, ROCK2 may be having a tumor suppressor role in this model." (PMID 26765561, 2016). "In addition, suppression of TGFBR2, but not ROCK2, led to a reduction in tumor micro-colony size at 3 weeks." (PMID 25686838, 2015). "Interestingly, treatment with 3-BP and doxorubicin showed no synergistic inhibitory effect on LLC cell growth in vitro, while exposure of NPC with conditioned medium from 3-BP or/and doxorubicin pre-treated tumor cells could still up-regulate HK2 and ROCK2 expression as compared with untreated NPC." (PMID 34650057, 2021). "Similar to our Y27632 findings, the knockout of either ROCK1 or ROCK2 in MDA-MB-231 cells did not affect tumor growth, whereas the intratumoral injection of anti-RhoA siRNA reduced tumor growth." (PMID 29535813, 2018). "Although cancerous cells were found that contained just one type of ROCK protein, no tumor cells were found that lacked both ROCK1 and ROCK2, further confirming that having one ROCK protein is essential for tumor formation." (PMID 26765561, 2016). "Collectively, analysis of ROCK1 and ROCK2 protein expression in tumors and tumor derived cell lines suggests that the absence of ROCK1 and ROCK2 is incompatible with tumorigenesis." (PMID 26765561, 2016). "Using a tumor xenograft system, SVR cells stably expressing non-targeting control, ROCK1, or ROCK2 shRNA plasmids were seeded onto 1 mm2 gelatin sponges and implanted onto the chorioallantoic membrane of 8 day post-fertilization chicken eggs." (PMID 22934846, 2013). "Together, this suggests that the effect of RhoA on tumor cell proliferation could be independent of its downstream effectors ROCK1 and ROCK2." (PMID 29535813, 2018). "However, we did not observe a significant correlation between tumor size and ROCK1 or ROCK2 mRNA expression." (PMID 26468005, 2015).
cancer (83 papers, 2009 to 2025). A tumor composed of atypical neoplastic, often pleomorphic cells that invade other tissues. "Among various drug targets, Rho-associated protein kinase 2 (ROCK2) has emerged as a promising target for a range of diseases, including cancer, cardiovascular disease, and neurological disorders." (PMID 40359277, 2025). "Meanwhile, by sponging miR-181a-5p, circNSUN2 increased the expression of Rho-associated coiled-coil-containing protein kinase 2 (ROCK2), a key molecule in cancer growth, subsequently improve the proliferation and migration of CRC cells." (PMID 37273004, 2023). "ROCK2 has been linked to a variety of cellular functions such as actin organization, neuronal growth cone guidance, cell migration, synaptic transmission, and cancer cell invasion and proliferation." (PMID 40359277, 2025). "Furthermore, several somatic mutations in genes encoding ROCK-1 or ROCK-2, leading to a gain-of-function, have been identified in several cancers and especially in colorectal cancer." (PMID 32770034, 2020). "ROCK2 has been implicated in many cellular functions, including actin organization, cell migration, neuronal growth cone guidance, synaptic transmission as well as cancer cell invasion and proliferation." (PMID 28554330, 2017). "Next, we examined subcellular localization of CXADR, which was recently reported to be required for adherens and tight junction formation during porcine blastocyst development (Kwon, Kim & Choi, 2016) and shown to directly associated with ROCK1 and ROCK2 in human carcinoma cells." (PMID 27077008, 2016). "The Rho associated coiled-coil containing protein kinase (ROCK1 and ROCK2) and myotonic dystrophy-related Cdc-42 binding kinases (MRCKα and MRCKβ) are critical regulators of cell proliferation and cell plasticity, a process intimately involved in cancer cell migration and invasion." (PMID 37630974, 2023). "Both PIM1 and ROCK2 promote cell migration in cancer, and there may be some associations." (PMID 36982538, 2023). "Intriguingly, high expression of ROCK2 predicted worse OS in pan-cancer patients from TCGA database." (PMID 39406918, 2024). "It is worth noting that some miRNAs target both ROCK1 and ROCK2, such as miR-124 and miR135a in cancer cells." (PMID 35043239, 2022). "In BC cells, the oncogene BCL6 and cancer progression-related genes ROCK2 and CDH11 have been identified as targets of miR-127 in BC." (PMID 36371182, 2022). "Previously, it had been shown that inhibition of ROCK1 and ROCK2, in addition to MRCKα and MRCKβ strongly impaired migration of cancer cells." (PMID 33921698, 2021). "ROCK1 and ROCK2 are central regulators of actin-myosin contractility and actin cytoskeleton dynamics and are being discussed as potential therapy targets in cancer and other diseases." (PMID 33777943, 2021). "Knocking down the expression of ROCK-2 also increased the invasive capacity of SW620 cancer cells, by a median factor of 1.99." (PMID 32770034, 2020). "Autophagy, which is related to differentially expressed miR-142-3p and ROCK2, plays an essential role in circRNA-regulated cancer progression and chemoresistance." (PMID 33153478, 2020). "We show that both the pharmacological and molecular inhibition of ROCK-1 and ROCK-2 induce SW620 cancer cell invasiveness, by promoting the activity of the pro-invasive voltage-gated sodium channel NaV1.5 activity." (PMID 32770034, 2020). "A major consequence of inhibition of ROCK2 was increased radio-sensitization and consequently increased cell death of cancer cells, in vitro." (PMID 31488179, 2019). "All of these marine natural products were growth inhibitors for different human pathogenic bacteria, and compound 22 showed ROCK2 inhibition (IC50 > 20 μM) and cytotoxic activity against HCT-116 and PC3 cancer cells in vitro with IC50 > 40 mM." (PMID 31450856, 2019).